RNU7-190P (RNA, U7 small nuclear 190 pseudogene)
Gene: Small nuclear RNA gene on chromosome 2 (117,139,715 to 117,139,775, reverse strand). Ensembl gene ENSG00000239185.
Homologues: Orthologues: chimpanzee U7 (98% identical), macaque U7 (85% identical). Paralogues in human: RNU7-6P (89% identical), RNU7-18P (85% identical), RNU7-25P (85% identical), RNU7-28P (85% identical), RNU7-40P (85% identical), RNU7-41P (85% identical), RNU7-7P (85% identical), RNU7-1 (84% identical), RNU7-11P (84% identical), RNU7-128P (84% identical), RNU7-14P (84% identical), RNU7-23P (84% identical), and 142 more.